RNU4-60P (RNA, U4 small nuclear 60, pseudogene)
Gene: Small nuclear RNA gene on chromosome 19 (42,472,875 to 42,473,009, forward strand). Ensembl gene ENSG00000253048.
Homologues: Orthologues: dog U4 (55% identical), dog U4 (54% identical), dog U4 (53% identical), rat LOC120097290 (49% identical), guinea pig U4 (48% identical). Paralogues in human: RNU4-67P (59% identical), RNU4-15P (57% identical), RNU4-36P (57% identical), RNU4-58P (57% identical), RNU4-28P (56% identical), RNU4-40P (56% identical), RNU4-66P (56% identical), RNU4-86P (56% identical), RNU4-90P (56% identical), RNU4-10P (55% identical), RNU4-49P (55% identical), RNU4-72P (54% identical), and 82 more.